HDAC4 (histone deacetylase 4)
Diseases named in the same sentence as HDAC4 in open-access papers (continued):
Sharing a sentence is not in itself a finding about the gene and the disease.
tumor (continued). "EWAS results from bulk tumor tissue identified only one or two CpGs in HDAC4 and IGF1R as differentially hydroxymethylated in either cell type-adjusted or unadjusted model." (PMID 36909536, 2023). "Further, CHDI0039 mono-treatment reduces tumor mass and weight in high HDAC4-expressing HNSCC in vivo (CAM model)." (PMID 36982651, 2023). "The neuronal-like cell types had lower expression of HDAC4 across all tumor types compared to the non-tumor tissue." (PMID 36909536, 2023). "Non-small cell lung cancer and melanoma are the second tumor types for frequency of genetic alterations in HDAC4 (15–17% of cases)." (PMID 36762207, 2023). "On the other hand, HIF1α is destabilized by acetylation, and its deacetylation by HDAC4 maintains higher protein levels and allows it to execute its tumor-promoting functions." (PMID 36901692, 2023). "This tumor suppressive effect is thought to be mediated by inhibition of a variety of target genes, including HDAC4." (PMID 36762207, 2023). "High expression of HDAC4 was detected in either tumor tissues derived from radiotherapy responders or radioresistant EC cells." (PMID 35193602, 2022). "Together, these results demonstrated that HDAC4 plays a pro-oncogenic role in GC by promoting tumour cell growth and migration." (PMID 35637410, 2022). "It is reasonable that pan-HDAC inhibitor, panobinostat, in current study showed greater anti-tumor effect than single HDAC4 knockdown in HCC cells/allografts." (PMID 36185276, 2022). "In the mouse model of lung and abdominal metastasis, we observed that the number of metastatic tumour nodules is lower in the Sh-HDAC4 group than in the control group." (PMID 35637410, 2022). "In conclusion, HDAC4 is a tumor promoter and chemoresistance factor in GC and alteration in HDAC4 status seems to be a predictive factor for the overall survival of GC patients." (PMID 36358890, 2022). "IHC staining further confirmed that HDAC4 knockdown inhibits MEKK3 expression in the subcutaneous GC xenograft tumour model." (PMID 35637410, 2022). "In vitro experiments using a cell line suggests that RGN exhibits anti-tumor effects through the suppression of histone deacetylase 4 (HDAC4)." (PMID 36234722, 2022). "The tumour growth was slower and tumour volume and weight were lower in the Sh-HDAC4 group than in the control group." (PMID 35637410, 2022). "In line with this, the knockdown of HDAC4 in several cancer cell lines was found to stimulate p21 expression and consequently inhibit tumor cell proliferation in vitro and tumor growth in vivo." (PMID 35897717, 2022). "To further verify the role of HDAC4 in GC cell proliferation and metastasis in vivo, we established a xenograft tumour model." (PMID 35637410, 2022). "To uncover the molecular mechanism by which HDAC4 regulates GC tumour progression, we compared the transcriptome profiles of SGC7901 cells with stable HDAC4 knockdown with controls by RNA-seq analysis." (PMID 35637410, 2022). "In conclusion, our present study highlighted an important role of HDAC4 in promoting tumor growth and metastasis in NPC." (PMID 33542203, 2021). "While many HDAC4 targets have been identified, we focused on HIF1α, one of the central players of tumor progression and drug response and VEGFA, one of the best-characterized HIF1α targets." (PMID 34359722, 2021). "HDAC4 regulates the expression of E-cadherin, N-cadherin, Snail and Slug, and cyclin D1 to promote tumor growth and metastasis in NPC." (PMID 33542203, 2021). "In conclusion, our study reveals that circKEAP1 competitively binds miR-141-3p to abolish the suppressive effect of miR-141-3p on KEAP1, which results to suppress the NRF2/HDAC4 signal pathway and inhibit tumor progress." (PMID 34136401, 2021). "NetICS suggests that overexpression of HDAC4 - which is frequently dysregulated in human malignancies - drives tumor growth in HCC." (PMID 34348664, 2021).
tumor (continued). "Collectively, our results indicate that HDAC4 facilitates tumor growth and metastasis via promoting G1/S transition and EMT in NPC." (PMID 33542203, 2021). "The tumor weight indicated that the HDAC4 overexpression group showed increased subcutaneous tumor growth compared with the 6-10B-vector cell group." (PMID 33542203, 2021). "Intriguingly, HDAC4 deacetylates and stabilizes HIF1α, one of the central players of tumor progression and drug response." (PMID 34359722, 2021). "ZIP4-KO resulted in greatly diminished expression of ZIP4 and HDAC4 in tumor sections, with reduced ALDH1A expression." (PMID 34359722, 2021). "Restoration of miR-22 expression suppresses cell proliferation and endogenous expression of HDAC4 protein; miR-22 transfection delays tumor formation and reduces tumor size in vivo." (PMID 32906681, 2020). "We suggest that a key intermediate must exist between HDACs and HK2, mediating the regulation of HK2 expression levels and tumour metabolism by HDAC4 and HDAC5." (PMID 32519437, 2020). "IHC results also manifested that HDAC4 expression was inversely correlated with PRL-3 in these tumor samples." (PMID 31887658, 2020). "While we observed increased Hdac4 expression in UpkII-SV40T mouse tumor tissue compared to WT urothelium, Hdac4 was primarily detected in the cytoplasm throughout the urothelium." (PMID 31137849, 2019). "This is partially due to higher levels of HDAC4 expression in hypoxic tumor regions with increased levels of HIF1α expression, as demonstrated using IHC." (PMID 30837601, 2019). "Several tumor types also feature an overexpression of HDAC4 as a prognostic marker of poor survival and aggressive tumor progression." (PMID 31067680, 2019). "miR-140-5p is a tumor suppressor that downregulates HDAC4, a histone deacetylase that contributes to tumorigenesis, and competitive binding by Malat1 with miR-140-5p was shown to increase HDAC4 activity." (PMID 31616462, 2019). "We categorized BC tumor tissue samples relative to tumor stage and morphology in a separate BC cohort and used q-RT-PCR to examine expression of HDAC4, -7, and -9." (PMID 31137849, 2019). "While not detected in nuclei, we observed positive but weak cytoplasmic staining for Hdac4 and -7 in the areas of this tumor enriched with SqD." (PMID 31137849, 2019). "In this interactive functional loop, silencing HDAC4 or using pan-HDAC inhibitor SAHA inhibits tumor cell growth and migration and increases cell apoptosis and autophagy." (PMID 30176876, 2018). "The natural compound curcumin, through HDAC inhibition and HDAC4 level depletion, reduced tumor growth and significantly increased survival in the Smo/Smo transgenic MB mouse model displaying HDAC4 overexpression." (PMID 30560106, 2018). "HDAC4 is targeted by miR-1 and miR-155; in contrast with the HDAC expression data, exogenously expressed miR-1 that putatively should interfere with HDAC4 acts as a tumor suppressor gene prolonging survival in an animal model." (PMID 29234674, 2017). "The results showed that HDAC4 expression was significantly up-regulated in tumor tissues compared with the paired normal tissues (P<0.001)." (PMID 27295551, 2016). "Given that MMPs and EMT were involved in tumor cells metastasis, we further investigated the link between HDAC4 expression and E-cadherin, Vimentin, MMP2 and MMP9 expression." (PMID 26441331, 2015). "We show that miR-125a-5p directly inhibits expression of the HDAC4 gene, resulting in tumor suppression in vitro and in vivo." (PMID 25504437, 2015). "Even though the expression level for HDAC4 did notvary within the GL tumors, the expression of HDAC4 correlates positively witha better survival time across all tumor samples.The biological significance of this observation needs further clarification." (PMID 25791281, 2015).
tumor (continued). "Indicative of a tumor suppressor function of HDAC4 is the observation that HDAC4 was down-regulated in 15 of 18 urothelial cancer cell lines." (PMID 26206152, 2015). "Conversely, silencing of HDAC4 abolish anti-miR-125a-5p-induced growth, invasion and migration as well as tumor growth/metastasis." (PMID 25504437, 2015). "Statistical analysis showed that high HDAC1 or HDAC4 mRNA expression was significantly correlated with advanced clinical stage (P=0.003 or 0.030, respectively) and poor tumor response of patients (P=0.004 or 0.001, respectively)." (PMID 24830600, 2014). "Tumor profile analysis reveals that LRP8 and HDAC4 are associated with immunotherapy outcomes." (PMID 41159493, 2026). "Overall, these findings suggested that overexpression of HDAC4 could negatively impact tumor immunogenicity." (PMID 40361444, 2025). "The accumulation of HDAC4 in the nucleus reduces the acetylation level of HIF1α, enhancing the stability and transcriptional activity of HIF1α and increasing the adaptability of tumour cells to hypoxic environments." (PMID 39778006, 2025). "Given the significant role of HDACs in tumor progression, metastasis, and drug resistance, we hypothesize that targeting HDAC4 and HDAC8 will enhance doxo sensitivity, promote apoptosis, and inhibit tumor growth." (PMID 40332124, 2025). "Inhibition of HDAC4 enhances the cytotoxic effects of cisplatin and impedes tumor cell growth." (PMID 39512688, 2024). "Interestingly, we observed an inverse association between HDAC-4 expression and lower FIGO stage and tumor T-status." (PMID 38790909, 2024). "The pro-survival activity of HDAC4 can also be exploited by controlling the tumor microenvironment." (PMID 36762207, 2023). "The three class II HDACs (HDAC4, HDAC5, HDAC6) exhibited similar expression patterns, with predominantly cytoplasmic staining, that was higher in epithelial rich TETs (B3, C) and more advanced tumor stages, while it was also associated with disease recurrence." (PMID 36901692, 2023). "In this context, the functions of HDAC4 are tumor suppressive." (PMID 36762207, 2023). "More than 50% of the dhmCpGs in HDAC4 for each tumor type were in the gene body." (PMID 36909536, 2023). "Thus, we further discovered that MORC2 affects the proliferation of tumor cells by HDAC4 regulating cell senescence." (PMID 36234785, 2022). "Moreover, the IHC results of tumor tissues also showed that sh-hsa_circ_0003258 had lower expression of HDAC4 and ARHGAP5 in the lungs compared with the vector." (PMID 34986849, 2022). "In addition, IHC analysis revealed decreased expression of Ki-67 in the subcutaneous tumours in HDAC4 knockdown GC cells." (PMID 35637410, 2022). "However, higher expressed HDAC4 (*p < 0.05) and lower expressed Wee 1 (***p < 0.0001) mRNA were observed in tumor tissues than that of the matched normal tissues, respectively." (PMID 35432472, 2022). "Moreover, in this study, we provided direct evidence that HDAC4 promotes tumor growth and metastasis in NPC." (PMID 33542203, 2021). "Elevated KEAP1 could inhibit the expression of NRF2 and HDAC4, and then abolish the suppression of HDAC4 for the tumor suppressor miRNAs miR-1 and miR-206, which result to repress the cell proliferation." (PMID 34136401, 2021). "In addition, compared to control and ZIP4-KO mice, the mice in the groups treated with the two HDACis (PANO and LMK-235) and HDAC4-KD shared an interesting commonality: these reagents significantly blocked tumor metastases on the peritoneal walls." (PMID 34359722, 2021). "Taken together, our results found circKEAP1 could serve as a sponge for miR-141-3p to regulate KEAP1 and activate the KEAP1/NRF2/HDAC4 signal pathway via the ceRNA mechanism to repress tumor growth." (PMID 34136401, 2021). "More importantly, HDAC4 expression was higher in LN metastases than in primary tumor tissues." (PMID 33542203, 2021).
tumor (continued). "Notably, immunohistochemistry (IHC) demonstrated that the HDAC4 protein levels were substantially higher in primary tumor tissues and LN metastases than in normal nasopharyngeal epithelial tissues." (PMID 33542203, 2021). "In addition, HDAC4 knockdown in S18 and 5-8F cells resulted in a significant decrease in subcutaneous tumor growth, as shown by measuring the tumor weights." (PMID 33542203, 2021). "We also showed that the HDAC4 inhibitor tasquinimod suppresses tumor growth in NPC." (PMID 33542203, 2021). "At a functional level, HDAC4 inhibition favored cisplatin cytotoxicity and reduced tumor growth." (PMID 31703394, 2019). "Finally, we used a xenografted tumor model to establish that the inhibition of HDAC4 expression was also observed in vivo." (PMID 27935863, 2017). "HDAC4 and HDAC7 have been implicated in tumour growth, metastasis, and chemosensitivity." (PMID 28883618, 2017). "Overall, these results suggest that miR-125a-5p blocks tumor development by targeting HDAC4." (PMID 25504437, 2015). "Indeed, overexpression of HDAC4 abolished miR-125a-5p-mediated inhibition in growth, invasion, migration, tumor growth and metastasis in R2N1d cells." (PMID 25504437, 2015). "Additionally, Tasquinimod was reported to target HDAC4 to inhibit tumor proliferation." (PMID 37138869, 2023). "However, the molecular mechanism regarding HDAC4 regulated tumor metabolism and tumorigenesis remains unclear until our current work." (PMID 35864951, 2022). "In HER2− tumours, baseline expression of 48 genes associated with poor antiproliferative response (p < 0.005) including PERP and YWHAQ, the two most significant, and the transcription co-regulators (SAP130, HDAC4, and NCOA7) which were among the top 16 most significant." (PMID 31892336, 2019). "Notably, several HDAC genes, such as HDAC4 and HDAC10, showed significant, focal copy number loss, which is consistent with the experimental evidence that certain HDAC genes may serve as tumor suppressors during tumorigenesis." (PMID 30760718, 2019). "Notably, elevated HDAC-1 expression was significantly associated with increased tumor proliferative capacity, enhanced HDAC-4 expression with the absence of distant metastases and elevated HDAC-6 expression with earlier histopathological stage." (PMID 26502922, 2015). "Elevated HDAC-4 expression was significantly associated with the absence of organ metastases (p = 0.0453) and borderline with the absence of lymph node metastases (p = 0.0571) and tumor proliferative capacity (p = 0.0576)." (PMID 26502922, 2015). "Among the HDAC family, HDAC4 and HDAC8 have gained significant attention because of their distinct roles in tumor biology." (PMID 40332124, 2025). "On the other hand, class IIA and IIB HDACs (HDAC4/5/7/9 and HDAC6/10, respectively) exhibit both up- and downregulation in tumors depending on the tumor type." (PMID 39063083, 2024). "Histone deacetylase 4 (HDAC4) is similarly upregulated in NPC, where it binds to the E-cadherin promoter, repressing its transcription and driving tumor progression and metastasis." (PMID 39695216, 2024). "HDAC4 and IGF1R had differentially hydroxymethylated CpGs and increased expression in OPCs across all four of our tumor types." (PMID 38688903, 2024). "Consistently, Rh4 reduced the expression levels of HDAC4, IL-6 and p-STAT3 in tumor tissues of nude mice intratumorally injected with LPS as comparison to the LPS group." (PMID 37843550, 2023). "ADEM10, EPHB2, HDAC4, and SEPP1 in CRC inhibit cell migration, invasion, tumor growth, and liver metastasis through the SP1." (PMID 36798788, 2023). "HDAC4 and IGF1R had differentially hydroxymethylated CpGs and increased expression in oligodendrocyte precursor cells across all four of our tumor types." (PMID 36909536, 2023). "We identified two genes, HDAC4 and IGF1R, in our pediatric CNS tumors that were both epigenetically and transcriptionally altered in comparison to non-tumor pediatric brain tissue." (PMID 36909536, 2023).
tumor (continued). "The upregulation of hsa_circ_0003258 promotes tumour formation via the hsa_circ_0003258/miR 653p/ARHGAP5 axis, as well as the hsa_circ_0003258/IGF2BP3/HDAC4 axis, according to a recent study." (PMID 36840946, 2023). "In addition, HDAC4 overexpression was investigated in esophageal carcinoma and was found to be significantly correlated with a higher rate of cell proliferation and tumor migration and lymph node metastasis, resulting in a higher tumor pathological grade and lower survival rate." (PMID 35897717, 2022). "Upregulation of hsa_circ_0003258 drives tumor progression through both hsa_circ_0003258/miR-653-5p/ARHGAP5 axis and hsa_circ_0003258/IGF2BP3 /HDAC4 axis." (PMID 34986849, 2022). "Our previous report demonstrated the potential radiosensitization of HCC with a pan-HDACi (panobinostat) and specific HDAC4 knockdown HCC cells to impair DNA repair process and delay ectopic HCC tumor progression." (PMID 36185276, 2022). "Immunoblot analysis confirmed that HDAC4 protein levels were significantly increased in murine and human HCC tumor tissues." (PMID 34348664, 2021). "Both genetic manipulations (such as ZIP4 or HDAC4 KO/KD) and HDACi (PANO or LMK-235) were mainly aimed at targeting ZIP4-dependent CSCs and CDDP were mainly aimed at targeting the bulk tumor cells." (PMID 34359722, 2021). "Our data showed that HDAC4 promotes NPC cell proliferation, invasion, and migration in vitro and tumor growth and lung metastasis in vivo." (PMID 33542203, 2021). "Taken together, these data indicated that HDAC4 knockdown suppressed the proliferation, invasion and migration abilities of NPC cells in vitro as well as NPC tumor growth in vivo." (PMID 33542203, 2021). "Expression of HDAC1 (p = 0.02), HDAC3 (p = 0.04), HDAC4 (p = 0.001), as well as HDAC8 (p < 0.001) was significantly higher in M3 tumours compared to D3 tumours." (PMID 33316946, 2020). "It has been also demonstrated that the normal function of this tumor suppressor miRNA is to down-regulate a number of putative oncogenes including validated miR-22 targets MAX, MYCBP, HDAC4, HDAC6, CDK6, CDKN1A and NCoA1." (PMID 29716630, 2018). "One study indicated that NAC1 can form 300–500 kDa complexes in tumor cells, however, limited interaction partners of NAC1 like HDAC4, Miz1 have been reported and it is unclear how they work together." (PMID 29163184, 2017). "We further demonstrate that normal function of this tumor suppressor microRNA is to down-regulate a number of putative oncogenes including validated miR-22 targets MAX, MYCBP, HDAC4, HDAC6, CDK6, and NCoA1." (PMID 26244872, 2015). "This correlation between HDAC4 expression and tumor grade was studied in CGGA and three validation sets showing that HDAC4 expression differed among various grades and was downregulated for higher grades." (PMID 25557107, 2015). "Interestingly, HDAC1, HDAC2, HDAC4, and HDAC11 showed a significant upregulation in tumor compared to normal liver tissue." (PMID 39529166, 2024). "As with HDAC4, the differences between each cell type of each tumor type and same cell type of non-tumor tissues were also not statistically significant." (PMID 38688903, 2024). "HDAC4 promotes proliferation and invasion and is considered as a negative prognostic marker in regard to tumor grade and survival." (PMID 36982651, 2023). "To next test whether the enzymatic activities of these HDACs play a role in tumor cell fitness, we treated pG-2 and HCC1806 cells with specific inhibitors for HDAC8 (PCI-34051) and HDAC4/7 (TMP195) and subsequently assessed tumor cell proliferation." (PMID 35016723, 2022).